HOXA13 (homeobox A13)
Diseases named in the same sentence as HOXA13 in open-access papers (continued):
Sharing a sentence is not in itself a finding about the gene and the disease.
cervical carcinoma (6 papers, 2018 to 2023). A carcinoma arising from either the exocervical squamous epithelium or the endocervical glandular epithelium. "Hsa-miR-1249-3p resulted as overexpressed in human epithelial cells/cervical tissues compared to cervical carcinoma cells/precancerous tissues, with the opposite expression of its validated target gene HOXA13." (PMID 38129477, 2023). "Cervical cancer cell lines HeLa, SiHa and CasKi showed HOXA13 mRNA levels of 3.8 × 10–3 (± 3 × 10–3), 2.8 × 10–2 (± 1.3 × 10–2) and 6.6 × 10–3 (± 4.6 × 10–3), respectively." (PMID 38129477, 2023). "LncRNA DLEU1 promoted cervical cancer cell proliferation and invasion via the miR-381/HOXA13 axis." (PMID 36561319, 2022). "In cervical cancer, miR-381 inhibits HOXA13 and FGF7, which can facilitate invasion and migration." (PMID 33324542, 2020). "By sponging miR-381 in cervical cancer cells, DLEU1 inhibits miR-381, which directly targets HOXA13." (PMID 33324542, 2020). "The C insertion after base 1042 and/or a G to C substitution at base 1113 in intron 1 but not in exon of the HOXA13 gene in cervical carcinoma cells has also been detected." (PMID 37393256, 2023). "The rest of the HOXA members (including HOXA2‐9 and HOXA13) showed very small differences between cervical cancer and normal controls, with no statistical significance." (PMID 34606634, 2021).
colon cancer (6 papers, 2021 to 2024). "HOXA13 was expressed more in the normal colon tissues when compared with colon cancer, and HOXA13 expression was associated with TNM stage of patients." (PMID 34606634, 2021). "Studies have shown that HOXA13 (Human class I homeobox A13) is involved in Wnt signaling and β-catenin translocation and promotes colon cancer cell proliferation, migration, and invasion." (PMID 38720110, 2024). "WNT/β-catenin pathway is also under HOXA13 regulation in colon cancer, leading tumor formation promotion." (PMID 38129477, 2023). "HOXA13 is a potential oncogene, which acts by promoting the nuclear translocation of β-Catenin, thereby maintaining the proliferation and metastasis of colon cancer." (PMID 35836256, 2022). "In vitro studies showed that HOXA13 promoted colon cancer cell proliferation, migration, and invasion, and in vivo studies showed that HOXA13 promoted tumor formation through the Wnt/β-Catenin pathway." (PMID 34075028, 2021). "HOXA13 might bind to β-catenin in epithelial cells and promote, in turn, the nuclear accumulation of β-catenin, as previously demonstrated in colon cancer cells." (PMID 38129477, 2023). "HOXA13 promotes the malignant phenotype of colon cancer cells by promoting the nuclear translocation of β-catenin and promotes the proliferation, migration and invasion of colon cancer cells." (PMID 35836256, 2022). "We have recently shown their de-regulation in colon cancer, describing the absence of expression of HOXA13, HOXB13, HOXC13 and HOXD13 in the normal colon mucosa, a slight increase in expression in the transitional mucosa, up to in many cases over-expressed in the tumor." (PMID 34208964, 2021).
esophageal squamous cell carcinoma (6 papers, 2019 to 2024). Esophageal squamous cell carcinoma (ESCC) is a type of esophageal carcinoma (EC) that can affect any part of the esophagus, but is usually located in the upper or middle third. "HOXA13 deregulation has been further associated with Disease Free Survival (DFS) in esophageal squamous cell carcinoma (ESCC)." (PMID 31137568, 2019). "It was demonstrated that HOTTIP transcriptionally regulates HOXA13 in esophageal squamous cell carcinoma cells to promote carcinogenesis and metastasis." (PMID 36438902, 2022). "Moreover, HOXA13 expression negatively affects cisplatin sensitivity in human esophageal squamous cells and overall survival in patients with esophageal squamous cell carcinoma." (PMID 32296636, 2020). "In addition, HOTTIP functions as a ceRNA to bind miR-30b, which promotes HOXA13 expression in esophageal squamous cell carcinoma (ESCC)." (PMID 31575017, 2019).
breast carcinoma (5 papers, 2018 to 2023). "Aberrantly expressed HOXA6 and HOXA13 were also observed in breast cancer." (PMID 32296636, 2020). "GR has also been shown to be a inducer of EMT in breast cancer cells, and overexpression of the homeobox protein HOX-A13 (HOXA13) in renal tubular epithelial cells can inhibit EMT by activating GR signaling." (PMID 36304156, 2022).
hypospadias (5 papers, 2018 to 2026). Hypospadias is the displacement of the urethral meatus on the ventrum of the penis. "A correlation between the low expression level of EGF, EGFR, and HOXA13 in the foreskin tissue and hypospadias cases indicates a possible cause of hypospadias." (PMID 37238140, 2023).
ovarian carcinoma (5 papers, 2019 to 2022). A malignant neoplasm originating from the surface ovarian epithelium. "It has been verified that LUCAT1 promotes malignant progression of ovarian cancer (OvCa) by regulating the miR-612/HOXA13 pathway." (PMID 35711895, 2022). "For instance, lncRNA LUCAT1 accelerated ovarian cancer progression via the modulation of miRNA-612/HOXA13 pathway." (PMID 35957833, 2022). "Two studies about ovarian cancer and overexpression of LUCAT1 have been described and revealed that LUCAT1/miR-612/HOXA13 pathway modulates ovarian cancer progression." (PMID 31591432, 2019).
glioblastoma (4 papers, 2015 to 2025). The most malignant astrocytic tumor (WHO grade IV). "While HOXA13 increases both proliferation and invasion, as well as inhibits apoptosis in glioblastoma multiform cells." (PMID 26800519, 2016). "Several reports have suggested that high expression of homeotic genes, including HOXA9, HOXA13, mesenchyme HOX2 (MEOX2), and HOXD4 is an indicator of poor prognosis in glioblastoma (GBM) patients." (PMID 34458259, 2021).
leukemia (4 papers, 2017 to 2021). A malignant (clonal) hematologic disorder, involving hematopoietic stem cells and characterized by the presence of primitive or atypical myeloid or lymphoid cells in the bone marrow and the blood. "The increased expression of HOXA9 could be found in most aggressive leukemia, and HOXA13 physically linked to tumor growth and angiogenesis." (PMID 34606634, 2021). "Many of the predicted transcription factors have a known role in hematopoiesis and leukemia development (Ikzf2, Pbx3, and Hoxa13 for upregulated genes and Fos, Nkx2-2, Gata2 for downregulated genes)." (PMID 31186416, 2019). "In addition, a novel NUP98 partner gene for HOXA13, with an expression pattern similar to HOXA9 in leukemic cell lines, implies that the NUP98-HOXA13 fusion protein, like the NUP98-HOXA9 fusion protein, may play a role in leukemia development via the same mechanism." (PMID 31426381, 2019).
liver cancer (4 papers, 2015 to 2024). An epithelial or non-epithelial malignant neoplasm that arises from the liver. "Our data are consistent with a pioneering study demonstrating that decreased expression of HOXA13 led to a clear reduction of HOTTIP expression in liver cancer-derived cell lines." (PMID 25889214, 2015). "In liver cancer cell lines and tumors, HOTTIP is closely associated with expression of HOXA13 and knockdown of HOTTIP decreases expression of HOXA13." (PMID 25912306, 2015). "Previous studies in foreskin fibroblasts show that HOTTIP knockdown decreases expression of 5′ HOXA genes, particularly HOXA13 and in liver cancer cells and tumors, there was a parallel expression of HOTTIP and HOXA13 and siHOTTIP decreased HOXA13 mRNA levels." (PMID 25912306, 2015). "However, in Panc1 cells transfected with siHOTTIP, there was only a slight decrease in HOXA13 expression, whereas siHOTTIP decreased HOXA13 in SNU-499 liver cancer cells and this was consistent with previous studies in liver cancer cell lines." (PMID 25912306, 2015). "Notably, HOXA13 and HOTTIP were found to be highly expressed in the same neoplastic hepatocyte populations and in liver cancer cell lines." (PMID 39329491, 2024).
lung adenocarcinoma (4 papers, 2018 to 2024). A carcinoma that arises from the lung and is characterized by the presence of malignant glandular epithelial cells. "We found that HOXA3 was low expressed in lung adenocarcinoma and had a protective effect on the prognosis of lung cancer patients; whereas HOXA11 and HOXA13 play oncogenic roles in lung adenocarcinoma 14-16." (PMID 35370463, 2022). "HOXA10, HOXA11, and HOXA13 might be useful targets to further mine the molecular pathogenesis of HOXA11 in early-stage lung adenocarcinoma." (PMID 29914539, 2018). "Moreover, YTHDC2 suppressed SLC3A2 by inhibiting Homeobox A13 (HOXA13) indirectly and was also found to affect system Xc- function in lung adenocarcinoma cells." (PMID 36185243, 2022).
esophageal cancer (3 papers, 2015 to 2024). A primary or metastatic malignant neoplasm involving the esophagus. "HOXA13, which is a marker of gut primordial posteriorization during development, has been shown to play a crucial role in tumorigenesis of the liver and bladder and in esophageal cancer." (PMID 36420138, 2022). "Among the HOXA genes, HOXA13, which is a marker of gut primordial posteriorization during development, has been shown to play a crucial role in tumorigenesis of the liver and bladder and in esophageal cancer." (PMID 25889214, 2015). "Co-expression of ANXA2 with HOXA13 and SOD2 has also been found to play a prognostic role in esophageal cancer." (PMID 38658569, 2024).
lymph node metastasis (3 papers, 2015 to 2023). "HOXA13 protein expression was significantly associated with tumor invasiveness (p = 0.020), tumor grade (p = 0.003), lymph node metastasis (p = 0.027), and recurrence (p = 0.043)." (PMID 37627895, 2023). "Statistical analysis revealed that HOXA13 overexpression was correlated with lymph node metastasis and poor histological differentiation." (PMID 25889214, 2015). "Analysis of the relationship between HOXA13 expression in paraffin-embedded PDAC samples and clinicopathological data indicates that patients with high HOXA13 expression exhibit increased lymph node metastasis, poor histological differentiation, and decreased overall survival." (PMID 25889214, 2015).
nasopharyngeal carcinoma (3 papers, 2023 to 2025). A carcinoma arising from the nasopharyngeal epithelium. "Spearman bivariate correlation analysis method was used to analyze the relationship between HOXA13 and Snail expression in nasopharyngeal carcinoma samples, and the result was positive correlation (r = 0.661, P < 0.05)." (PMID 37563232, 2023). "Further research showed that HOXA13 and Snail were highly expressed in nasopharyngeal carcinoma tissues (68.75% (44/64) and 62.50% (40/64), respectively), significantly higher than normal tissues (6.67% (2/30) and 13.33% (4/30)), respectively) (P < 0.05)." (PMID 37563232, 2023). "In another study in nasopharyngeal carcinoma cells (NPC), HOXA13 was downregulated due to knockdown of HOTTIP, and this subsequently led to the suppression of cell proliferation, invasion, and metastasis, and induced apoptosis." (PMID 40231344, 2025). "Nasopharyngeal carcinoma patients with high expression of HOXA13 or Snail had worse stage N, and neither of them had significant correlation with distant metastasis (stage M)." (PMID 37563232, 2023).
pancreatic ductal adenocarcinoma (3 papers, 2015 to 2023). An infiltrating adenocarcinoma that arises from the epithelial cells of the pancreas. "HOTTIP also was shown to be upregulated in human pancreatic ductal adenocarcinoma tissues and to promote pancreatic ductal adenocarcinoma cell proliferation, migration, invasion and resistance by regulating HOXA13." (PMID 28938659, 2017). "The latest study confirms that HOTTIP/HOXA13 axis promotes pancreatic ductal adenocarcinoma (PDAC) tumorigenesis." (PMID 26356815, 2015).
acute lymphoblastic leukemia (2 papers, 2019 to 2021). Leukemia with an acute onset, characterized by the presence of lymphoblasts in the bone marrow and the peripheral blood. "A chromosomal translocation between an upstream HOXA13 region and a downstream region of the BCL11B/CTIP2 locus has been described in T-cell acute lymphoblastic leukemia (T-ALL), resulting in a HOXA13 gene hyper-expression." (PMID 31137568, 2019).
Hypertension (2 papers, 2023 to 2025). The presence of chronic increased pressure in the systemic arterial system. "For the hypertension and atrial fibrillation pairing, signals implicating shared causal variants were seen on chromosomes 4, 7, 11, and 17, in the genes FGF5, HOXA13, in the region spanning LSP1 to TNNT3 and that spanning CYTH1 to USP36 respectively." (PMID 40538118, 2025).
lung carcinoma (2 papers, 2019 to 2023). "Hsa-miR-1249-3p has previously been reported to regulate HOXA13 gene in lung cancer cells." (PMID 38129477, 2023).
male infertility (2 papers, 2021 to 2022). The inability of the male to effect fertilization of an ovum after a specified period of unprotected intercourse. "Therefore, this competitive binding between lncRNA-miRNA can also lead to positive regulation of HOXA13 expression, resulting in male infertility." (PMID 36290414, 2022).
non-small cell lung carcinoma (2 papers, 2019 to 2025). A group of at least three distinct histological types of lung cancer, including non-small cell squamous cell carcinoma, adenocarcinoma, and large cell carcinoma. "The combined aberrant expression of HOXA13/HOTTIP related to the promotion of cell proliferation and in vivo/in vitro metastases, has been also reported in ESCC cells and in non-small-cell-lung cancer (NSCLC)." (PMID 31137568, 2019).
Wilms tumor (2 papers, 2022 to 2024). An embryonal neoplasm characterized by the presence of epithelial, mesenchymal, and blastema components. "Expression of mENL has been found to upregulate certain Hox genes, such as HoxA11 and HoxA13, in Wilms tumor and drive oncogenesis." (PMID 35395864, 2022). "Treatment with compound 1 during the incubation significantly inhibited overexpression of HoxA11 and HoxA13, showing degradation of mENL could downregulate aberrant gene expression in Wilms tumor." (PMID 35395864, 2022).
acute myeloid leukemia (1 paper, 2019). Acute myeloid leukemia (AML) is a group of neoplasms arising from precursor cells committed to the myeloid cell-line differentiation. "HOXA13 is able to frequently form a fusion gene with nucleoporin NUP98, named NUP98-HOXA13, playing a key role in acute myeloid leukemia (AML)." (PMID 31137568, 2019).
Barrett esophagus (1 paper, 2021). Esophageal lesion lined with columnar metaplastic epithelium which is flat or villiform. "We thus propose that Barrett’s esophagus and associated esophageal adenocarcinoma is the consequence of expansion of this gastro-esophageal HOXA13-expressing compartment following epithelial injury." (PMID 34099670, 2021). "Here we show HOX collinearity in the adult gut while Barrett’s esophagus shows high HOXA13 expression in stem cells and their progeny." (PMID 34099670, 2021). "Intriguingly, employing a mouse model that contains a reporter coupled to the HOXA13 promotor we identify single HOXA13-positive cells distally from the physiological esophagus, which is mirrored in human physiology, but increased in Barrett’s esophagus." (PMID 34099670, 2021). "HOXA13 overexpression appears sufficient to explain both the phenotype (through downregulation of the epidermal differentiation complex) and the oncogenic potential of Barrett’s esophagus." (PMID 34099670, 2021). "Here the authors report that the distal HOX gene HOXA13 is expressed in Barrett’s esophagus and in single cells of the physiological esophagus, and may underlie the phenotypic aspects of metaplasia and increase proliferation." (PMID 34099670, 2021). "In Barrett’s esophagus, gastric IM, and heterotopia of the upper GI-tract, a colon-like HOX gene expression is present, especially characterized by HOXA13 upregulation." (PMID 34099670, 2021).
bladder tumors (1 paper, 2019). "Moreover, since circulating bladder tumor cells can be carried in the urine, HOXA13 level has been also detected in this biological fluid." (PMID 31137568, 2019). "cDNA microarray analysis has highlighted that co-expression of HOXA13 and BLCA-4 could be able to discriminate low versus high grade bladder tumors." (PMID 31137568, 2019).
Cerebral ischemia (1 paper, 2023). Restriction of arterial blood supply to the brain associated with insufficient oxygenation to support the metabolic requirements of the tissue. "Our results are also in accordance with previous study demonstrating the protective role of the Snhg8/miR-384/Hoxa13/FAM3A axis in cerebral ischemia-induced neuronal apoptosis." (PMID 34853925, 2023).
colon adenocarcinoma (1 paper, 2021). "In contrast, colon adenocarcinoma showed a significant enrichment of TFs such as CDX2 (26.5%), CDX1 (24%), HOXA13 (22%), HNF4G (37.2%), and TCF4 (36%) in gained peaks; and FOS::JUNB (45.4%), FOS::JUND (47.5%) and JUNB (46.3%) in lost peaks." (PMID 34090364, 2021).
influenza infection (1 paper, 2024). "During influenza infection in the absence of the IFN-α/ß receptor, inflammatory and apoptotic responses may be initiated via induction of Ing1, Nr4a1, Polr2a, or Hoxa13." (PMID 38902760, 2024).
oral squamous cell carcinoma (1 paper, 2019). "In a further investigation, an opposite trend of HOXA13 expression has been detected in oral squamous cell carcinoma (OSCC): a prevalent HOXA13 expression, in the superficial side of the lesions, is significantly associated to a better prognosis of OSCC patients." (PMID 31137568, 2019).
osteosarcoma (1 paper, 2019). A usually aggressive malignant bone-forming mesenchymal neoplasm, predominantly affecting adolescents and young adults. "Accordingly, our study verified that upregulated NEAT1 increased expression of HOXA13, the target gene of miR‐34a‐5p, further leading to abnormal proliferation and apoptosis of osteosarcoma cells." (PMID 31044561, 2019). "Subsequently, HOXA13 expression in osteosarcoma tissues and paired paracancerous tissues was determined by qRT‐PCR." (PMID 31044561, 2019). "The mRNA levels of HOXA13 were remarkably elevated in osteosarcoma tissues compared to paracancerous tissues." (PMID 31044561, 2019). "To elucidate whether NEAT1 regulated HOXA13 expression via targeting miR‐34a‐5p, we detected expression levels of HOXA13 in osteosarcoma cells after altering NEAT1 or miR‐34a‐5p expressions." (PMID 31044561, 2019). "Both qRT‐PCR and Western blot results showed that overexpression of wild‐type NEAT1 upregulated HOXA13 expression in osteosarcoma cells, whereas mutant‐type NEAT1 did not disrupt base pairing between NEAT1 and miR‐34a‐5p." (PMID 31044561, 2019).
pituitary deficiency (1 paper, 2019). "We identified CBX2 regulated genes associated with polycystic ovary syndrome (PCOS) such as TGFβ, MAP3K15 and DKK1, as well as genes implicated in premature ovarian failure (POF) (i.e. POF1B, BMP15 and HOXA13) and the pituitary deficiency (i.e. LHX4 and KISS1)." (PMID 31745224, 2019).
placental insufficiency (1 paper, 2008). Failure of the placenta to deliver an adequate supply of nutrients and oxygen to the fetus. "To test this hypothesis we examined the developing heart, an organ that does not express Hoxa13 but is severely affected by placental insufficiency." (PMID 18483557, 2008).